HIF1A (hypoxia inducible factor 1 subunit alpha)
Diseases named in the same sentence as HIF1A in open-access papers (continued):
Sharing a sentence is not in itself a finding about the gene and the disease.
tumor (continued). "PTEN exerts its tumor suppressor function largely through antagonism of the PI3K/AKT pathway, thereby downregulating key angiogenic mediators such as VEGF and HIF-1α." (PMID 41226689, 2025). "Estrogen and G-1 have also been shown to elevate HIF-1α and VEGF levels, further promoting tumor angiogenesis." (PMID 40641933, 2025). "We first investigated the effects of HIF‐1α inhibitor PX‐478 and microtubule inhibitor BPR0C261 on tumour progression prior to imaging of tumour angiogenesis." (PMID 39757131, 2025). "Research indicates that tumor cells can drive angiogenesis by secreting various proangiogenic factors (VEGF-A and HIF-1α), thereby forming a specific microenvironment that promotes tumor metastasis." (PMID 40438141, 2025). "Recent studies have demonstrated that upregulating HIF-1α in CD8+ T cells through VHL knockdown enhances cytotoxic function and suppresses tumor growth." (PMID 40343532, 2025). "Metabolites such as lactate, produced by tumor cells, can stabilize HIF-1α, reinforcing TAM polarization toward a tumor-promoting phenotype and sustaining an immunosuppressive TME." (PMID 40076729, 2025). "MCT1-mediated lactylation plays a key role in stabilizing HIF1A, enhancing KIAA1199 transcription to promote tumor angiogenesis." (PMID 39979245, 2025). "HIF-1α and VEGF are very closely related, and they induce angiogenesis and promote tumor growth by interacting with the MEK, PI3K/Akt, or FAK signaling pathways, inducing vascular permeability and the expression of genes for cell proliferation." (PMID 41585262, 2025). "Tumor-derived exosomes activate the toll-like receptor 2 (TLR2)/NF-κβ signaling axis in macrophages, driving HIF-1α-mediated upregulation of GLUT-1." (PMID 41463352, 2025). "Mechanistically, FABP5 improves HIF-1α activity by inhibiting its interaction with Factor Inhibiting HIF (FIH), thereby enhancing lipid accumulation and tumor cell proliferation." (PMID 41357200, 2025). "Combining hypericin-mediated PDT with celecoxib blocks the COX-2/HIF-1α/VEGF pathway, mitigating hypoxia-driven VEGF rebound and improving tumour control." (PMID 39857765, 2025). "Under normoxic conditions, HIF-1α is tightly controlled by VHL protein, a tumor suppressor that acts as part of an E3 ubiquitin ligase complex." (PMID 41462905, 2025). "AIF levels in tumours are inversely correlated with hypoxia, which inhibits AIF expression through the hypoxia‐inducible factor‐1α (HIF1α)." (PMID 39866010, 2025). "Amplification or epigenetic modification of TERT (rs7734992, 5p15.33) plays a crucial role in ccRCC by maintaining cellular immortality, with HIF1A and EPAS1 regulating TERT expression, enhancing tumour survival under hypoxic conditions." (PMID 41326661, 2025). "Moreover, the duration for which HIF-1α expression is sustained within the tumor remains unclear." (PMID 40343532, 2025). "It has been reported in the literature that SRGN is a downstream target gene of HIF‐1α, and abnormal HIF‐1α/SRGN regulation affects tumour progression and metastasis." (PMID 41410182, 2025). "IHC staining was performed to detect the expression of USP35, STING, HIF-1α, and ICAM1 in the tumor tissues, and the results were consistent with those obtained in vitro." (PMID 41372134, 2025). "Hypoxia-inducible factor 1-alpha (HIF-1α) is a key transcription factor that regulates cellular adaptation to hypoxia and promotes tumor survival, angiogenesis, and metastatic progression." (PMID 41425711, 2025). "In signaling pathway interactions, PKM2 activates the NF-κB/p65 pathway to upregulate HIF-1α expression and transcriptional activity and induces VEGF-A secretion to promote tumor angiogenesis." (PMID 40842995, 2025). "In addition, activation of HIF1A under hypoxic conditions may promote endothelial barrier stabilization while simultaneously altering chemokine gradients—together contributing to reduced immune cell infiltration into the tumor microenvironment." (PMID 41465546, 2025).
tumor (continued). "Among the downstream targets of HIF1α, NT5E (CD73), an ecto-5′-nucleotidase, plays a pivotal role in the tumor microenvironment by converting extracellular AMP to immunosuppressive adenosine." (PMID 41463265, 2025). "Similar to tumor cells, M1 macrophages rely on aerobic glycolysis and the pentose phosphate pathway (PPP), with upregulation of HIF-1α-related signaling, promoting the production of lactate and succinate." (PMID 40873588, 2025). "In the HIF-1α overexpression group, increases in tumor volume and weight were accompanied by elevated YAP/TAZ expression within the tumors; conversely, the opposite effects were observed following HIF-1α inhibition." (PMID 41256331, 2025). "Key sites, including hypoxia-inducible factor 1-alpha (HIF1A), estrogen receptor, heat shock protein HSP 90-beta, and heat shock protein HSP 90-alpha, were highlighted for their critical roles in tumor progression and therapeutic resistance." (PMID 40418826, 2025). "Inhibition of hypoxia-induced factors like HIF-1α and SDF-1α—upregulated during anti-VEGF therapy—also limits TAM infiltration and enhances tumor sensitivity to radiotherapy and anti-angiogenic treatment." (PMID 40867316, 2025). "For instance, the levels of angiogenic factors (such as HIF-1α, VEGF, etc.)increase in VDR knockout mice, while calcitriol can inhibit VEGF-dependent tumor growth in normal mice." (PMID 40705722, 2025). "We further showed that T cell infiltration and activation were affected by the HIF-1α and HIF-2α status of the mouse tumours and that a similar relationship exists in human ccRCC20." (PMID 40473819, 2025). "HIF-1α activation boosts VEGFA mRNA and protein expression in hypoxic endothelial, stromal, and tumor cells, leading to VEGFR2 stimulation in adjacent cells." (PMID 41150799, 2025). "In the hypoxic tumor microenvironment of HCC, HIF-1α is activated as a transcription factor and directly upregulates the expression of LOXL2." (PMID 41019994, 2025). "As a rate-limiting enzyme for adenosine synthesis, CD73 drives tumor angiogenesis and promotes rapid tumor growth by promoting the expression of VEGF and HIF-1α." (PMID 40420185, 2025). "Specifically, it inhibits proliferation, adhesion, invasion, and metastasis in various tumor cells by modulating signaling pathways such as JNK, HIF-1α, PI3K/Akt, Nrf2, Wnt, JAK2-STAT3, and EGFR." (PMID 41156537, 2025). "By inhibiting aerobic glycolysis (e.g., by suppressing LDH/HIF-1α activity) and lipid anabolism (e.g., by reducing levels of hexadecanoic acid and FASN), curcumin markedly enhances the anti-tumor efficacy of sorafenib." (PMID 41515171, 2025). "Immunohistochemical analysis of tumor tissues revealed that Liensinine treatment led to a marked reduction in the expression levels of HK2, PDK1, and HIF-1α, while increasing the expression of IDH3B, UQCRC1, and phosphorylated AMPK (P-AMPK)." (PMID 40665352, 2025). "The tendency toward increased expression of GLUT‐1 and HIF‐1α, together with the extensive necrosis in SM, suggests that its microenvironment may be more hypoxic, which could at least partially explain the higher accumulation of adipophilin‐positive LD observed in this tumor." (PMID 40867038, 2025). "HIF-1α, a master regulator of hypoxia adaptation, drives the Warburg effect—promoting glycolysis and suppressing OXPHOS—to fuel tumor growth in low-oxygen microenvironments." (PMID 40507237, 2025). "In prostate cancer, lactylation stabilizes HIF-1α, activating KIAA1199 transcription and stimulating angiogenesis and tumor metastasis." (PMID 40994548, 2025). "Whereas OTUB2 acted as a tumor suppressor in OV, mechanistically, OTUB2 silencing destabilized SNX29P2, which subsequently prevented the degradation of HIF-1α." (PMID 40469292, 2025). "Some animal models have shown that aerobic exercise decreases HIF-1α and VEGF-A expression in tumor and adipose tissues." (PMID 41583457, 2025).
tumor (continued). "Elevated levels of HIF-1α subsequently stimulate the promotion of vascular endothelial growth factor and platelet-derived growth factor (PDGF) production, hence enhancing tumor angiogenesis." (PMID 40777037, 2025). "HIF-1α suppresses transcription of MHC class I heavy chains and antigen-processing components like TAP1/2 and LMP7, reducing surface presentation of tumour antigens, leading to diminished CD8+ T cell infiltration and impaired cytotoxic responses." (PMID 40806577, 2025). "Despite recognizing HIF-1α inhibition as a potential target to treat GBM, concerns still lie regarding ubiquitous expression in non-tumor tissues that can lead to potential systemic side effects." (PMID 41450919, 2025). "The aim of this study is to investigate the interactions of the molecules HIF-1α, LOX and ITGA 5 key players in tumor microenvironment and ECM remodeling—whose roles and interplay in drug resistance have been previously reported in preclinical studies." (PMID 39857068, 2025). "HIF-1α regulates Glut-1 expression via the PI3K/AKT/mTOR pathway, facilitating glucose uptake and glycolytic metabolism in tumor cells to provide energy support." (PMID 40725100, 2025). "Mechanistically, it is demonstrated that PLIN2 boosts HIF1α/SPP1 signaling in macrophages, thereby exerting pro‐tumor functions." (PMID 39921309, 2025). "HIF-1α facilitates GPC3 loading into sEVs, reducing intracellular GPC3 to suppress Wnt/β-catenin signaling and tumor growth." (PMID 40703510, 2025). "HIF-1α also regulates downstream targets like CCL7 and KIAA1199, forming a HIF-1α/CCL7/KIAA1199 axis that accelerates glycolysis and promotes tumor progression." (PMID 41220952, 2025). "Mechanistically, miR-184 targeted factor inhibiting hypoxia-inducible factor 1 (FIH-1), which in turn stabilised hypoxia-inducible factor 1-alpha (HIF-1α) and promoted tumour progression." (PMID 41379397, 2025). "Recent advances reveal intricate crosstalk between HIF-1α, mTOR, and PI3K/Akt pathways in regulating lactylation, which is profoundly shaped by tumor microenvironmental contexts." (PMID 40755753, 2025). "Mechanistic investigations have revealed that microbial colonies inhibit tumor angiogenesis by regulating gene expression within the vascular endothelial growth factor (VEGF) pathway, including genes such as MMP2 and HIF-1α." (PMID 40718835, 2025). "In the HIF-1 signaling pathway, hypoxia-inducible factor HIF1A is produced under hypoxic conditions, which drives the secretion of IL1B to enhance tumor cell proliferation, migration, and invasion." (PMID 40725477, 2025). "This upregulates hypoxia-inducible factor 1-alpha (HIF-1α), promoting angiogenesis and metabolic reprogramming to sustain tumor survival and proliferation." (PMID 40407535, 2025). "HAUSP (USP7), a deubiquitinating enzyme, can both deubiquitinate HIF‐1α to increase its stability and interact with CBP to mediate the acetylation of H3K56, enhancing the transcription of HIF‐1α and thereby inducing tumour EMT." (PMID 39778006, 2025). "The only report on a small molecule interacting with HIF-1α PAS-B domain is for acriflavine, which blocked heterodimerization with HIF-1β and led to the suppression of tumor growth and vascularization." (PMID 39968177, 2025). "Immunofluorescent microscopy confirmed nuclear SOX2 accumulation and co-expression of SOX2 and HIF-1α in dedifferentiated CSC-like cells, demonstrating tumor heterogeneity." (PMID 40358200, 2025). "Numerous studies indicate a correlation between hypoxia‐related proteins like HIF‐1α and CA9 as well as the stemness of tumor cells." (PMID 40873634, 2025). "At the molecular level, transcription factors such as STAT1, CEBPB, HIF1A, and REL, collectively drive MDSCs expansion, while chemokines like CCL3, CCL4, CCL8 and IL1B regulate their migration within the tumor microenvironment." (PMID 41252877, 2025). "We found that two representative molecules involved in EMT, CD44 and HIF1A, were expressed at high levels in IBC tumour cells." (PMID 40624675, 2025).
tumor (continued). "YC-1 suppresses the synthesis of HIF-1α and the signaling of VEGF, both of which are critical in tumor vascularization and metastasis." (PMID 40136686, 2025). "Nrf2 enhances angiogenesis under hypoxic conditions by stabilizing hypoxia-inducible factor 1 alpha (HIF-1α) and inducing VEGF expression, whereas inhibition of Nrf2 reduces tumor vascularization and growth in xenograft models." (PMID 41462607, 2025). "Under hypoxic conditions, the expression of hypoxia‐inducible factor‐1α (HIF‐1α) is significantly elevated, upregulating FAO‐related genes to maintain the energy demands of tumor cells." (PMID 40391753, 2025). "Under hypoxic conditions, FBP1 overexpression suppresses the mRNA expression of the HIF-1α target genes PDK1, LDHA, GLUT1, and VEGF, inhibiting tumor growth, migration, and glycolysis in BLBC." (PMID 40100307, 2025). "Within the tumor microenvironment, some cytokines and transcription factors, such as TGF‐β and HIF‐1α, not only induce fibroblast‐to‐CAF transformation but also perpetuate their glycolytic phenotype." (PMID 40772466, 2025). "Under hypoxic conditions, HIF transcription factors, particularly HIF-1α and HIF-2α, orchestrate various tumor-promoting processes, including angiogenesis, metabolic reprogramming, and metastasis." (PMID 40901111, 2025). "Anti-angiogenic control is provided by miR-138-5p (HIF-1α/VEGFA blockade) and miR-101, which thwarts vascular mimicry by targeting TGFβR1/SMAD2 in tumor cells and SDF1 in CAFs." (PMID 41007803, 2025). "Under hypoxic conditions, the upregulation of hypoxia‐inducible factor 1 alpha (HIF‐1α) and vascular endothelial growth factor (VEGF) in cells drives the formation of tumour neovascularisation." (PMID 40859871, 2025). "To do so, we measured mRNA levels of HIF-1α, HIF-2α, and VEGF in AT from normal and tumor kidney samples." (PMID 40995093, 2025). "This suggests that mutation in VHL leads to the initial activation of EPO expression in renal tumors, subsequently enhancing HIF1A activity, and sustained hypoxia is essential for maintaining EPO expression in the tumor microenvironment." (PMID 40332447, 2025). "For instance, a dandelion-derived polysaccharide was shown to inhibit the PI3K/Akt pathway, downregulating HIF-1α and VEGF expression, and thereby suppressing tumor angiogenesis." (PMID 40808836, 2025). "Under normoxic conditions, PHDs hydroxylate HIF-1α, targeting it for recognition and degradation via the von Hippel–Lindau (VHL) tumor suppressor pathway." (PMID 41036604, 2025). "Our data suggest that the coordinated metabolic shift via the PRCC‐TFE3/HIF1α/SREBP1 axis is a key mechanism by which PRCC‐TFE3 enhances cancer cell metabolism, promoting tumor development in TFE3‐RCC." (PMID 39807625, 2025). "Many studies have shown that the HIF-1α/VEGF signaling pathway has unique functions in angiogenesis and tumor growth." (PMID 40601668, 2025). "After accumulating at the tumor site, CQG NPs deplete GSH and produce oxygen, which inhibits HIF-1α expression and reduces NQO1 and NRF2 levels, disrupting the antioxidant system in tumor cells." (PMID 40791799, 2025). "HIF-1α and HIF-2α have been frequently found aberrantly overexpressed in many different tumor tissues, compared with healthy counterparts, directly linking tumor hypoxia to HIF factor expression." (PMID 41413686, 2025). "In PDAC, GPR35 promotes tumor proliferation, metabolic reprogramming and metastasis by activating AKT, stabilizing HIF-1α and regulating autophagy." (PMID 41459506, 2025). "Hypoxia-inducible factor-1α (HIF-1α) is a key regulator of cellular adaptation to low-oxygen conditions, while vascular endothelial growth factor (VEGF) and its receptor VEGFR2 drive tumor vascularization and correlate with poor prognosis." (PMID 41470183, 2025). "In cases where HIF1A is expressed, there was an upregulation of JAK2 and STAT5A proteins in tumor tissue, alongside EPOR." (PMID 40332447, 2025).
tumor (continued). "The expression of UBE2S in HIN and LIN was situated in the cytoplasm and nucleus, and the expression of HIF‐1α and FOXM1 in HIN and LIN was primarily situated in the nucleus of tumor cells." (PMID 41427004, 2025). "In GBM, high WWOX/HIF1A conditions leverage FAAH-mediated lipid signalling to resolve inflammation and induce tumour cell death, providing a potential mechanism for immune-mediated tumour suppression." (PMID 41007296, 2025). "Immunohistochemistry was performed to detect the expression of HIF‐1α, PFKFB3, and PFK‐1 in the tumor tissues of both groups." (PMID 40125821, 2025). "HIF-1α, stabilized under hypoxic conditions, further enhances HK2 transcription, linking tumor hypoxia in the TME to increased HK2 expression." (PMID 40520908, 2025). "Therefore, despite some potential beneficial effects of HIF-1α, overall, both HIF-1α and HIF-2α are currently thought to be involved in different stages of tumor development, their activity being modulated by numerous mutations, which are associated with tumor progression." (PMID 40227577, 2025). "One of the key features of clear cell RCC is the presence of hypoxic conditions within the tumor microenvironment due to aberrant VHL (von Hippel-Lindau) pathway activation, which stabilizes HIF-1α (hypoxia-inducible factor 1 alpha) and promotes angiogenesis." (PMID 40506992, 2025). "NK cells mediate tumor surveillance through IFN-γ/NF-α release, while hypoxic stress via HIF-1α-dependent mechanisms inhibits their activation and upregulates inhibitory receptors such as NKG2A." (PMID 41019983, 2025). "The tumor's increased oxygen consumption and immature vascular oxygen delivery system contribute to a sustained hypoxic TME, which stabilizes HIF‐1α by inhibiting prolyl hydroxylase (PHD)‐mediated degradation, leading to its accumulation." (PMID 40959206, 2025). "Within the tumor microenvironment (TME), hypoxia activates hypoxia-inducible factor 1-alpha (HIF-1α), a master transcriptional regulator of cellular responses to low oxygen levels." (PMID 40563999, 2025). "Genetic depletion or pharmacological inhibition of HIF1α and PHD1/3 disrupts FOXA1 stability and impairs tumor cell growth and motility, highlighting the therapeutic potential of targeting this axis." (PMID 40643528, 2025). "These intermediates modulate several intracellular signaling pathways, such as HIF-1α, mTOR, and PI3K/Akt, ultimately influencing tumor cell responses to chemotherapy and targeted therapies." (PMID 40115255, 2025). "Immunofluorescence staining of tumor sections revealed a positive correlation between NMT1 and HIF1α expression (r = 0.8213, p < 0.0001)." (PMID 40605065, 2025). "NT5E is associated with invasive cancer phenotypes and taken together, these results highlight the importance of NT5E, and its correlation with HIF1a, specifically in EAC tumor progression, which is known to be more invasive than ESCC." (PMID 41463265, 2025). "Nuclear HIF-1α levels were higher in stage IV tumors, whereas HIF-2α levels increased with tumor size." (PMID 41503066, 2025). "Under hypoxic conditions, the stability of HIF-1α is enhanced, and it translocases to the nucleus to form a heterodimer with HIF-1β, thereby activating downstream target genes and promoting tumor angiogenesis, metabolic reprogramming, and EMT." (PMID 41461671, 2025). "In HCC, HIF‐1α upregulates CD39 and CD73 in tumor cells, enhancing extracellular adenosine (eADO) production." (PMID 40667699, 2025). "Cancer cells are fast growing, and require new blood vessel growth, therefore HIF1α and VEGF are overexpressed within the tumor microenvironment." (PMID 41459064, 2025). "A high WWOX/HIF1A ratio in HCC defines a subgroup with enhanced metabolic detoxification, efficient oxidative phosphorylation, and reduced tumour invasion." (PMID 41007296, 2025).